FUT6 (fucosyltransferase 6)
Description:
[Isoform 1]: Catalyzes the transfer of L-fucose, from a guanosine diphosphate-beta-L-fucose, to the N-acetyl glucosamine (GlcNAc) of a distal alpha2,3 sialylated lactosamine unit of a glycoprotein- or a glycolipid-linked sialopolylactosamines chain or of a distal or internal lactosamine unit of a neutral glycoprotein- or a glycolipid-linked polylactosamines chain through an alpha-1,3 glycosidic linkage and participates in surface expression of the sialyl Lewis X (sLe(x)), Lewis X (Le(x)) and non sialylated VIM2 determinants. Moreover transfers fucose to H-type 2 (Fucalpha1-2Galbeta1-4GlcNAc) chain acceptor substrates and participates in difucosylated sialyl Lewis x determinants. Also fucosylates a polylactosamine substrate having a 6 sulfate modification at the GlcNAc moiety and gives rise to sialyl and non-sialyl 6-sulfo lewis X. Does not have activity towards type 1 ((Galbeta1-3GlcNAc)) and H-type 1 chain (Fucalpha1-2Galbeta1-3GlcNAc) acceptors substrates. [Isoform 2]: Does not have alpha(1,3)-fucosyltransferase activity.
Synonyms: Fuc-TVI; FucT-VI; FCT3A; FT1A; FLJ40754
Tractability: Antibody: UniProt places it where antibodies can reach, with high confidence; its Gene Ontology location is reachable by antibodies, with high confidence; UniProt predicts a signal peptide or a membrane-spanning region. PROTAC: a small molecule that binds it is known.
Target class: Enzyme; Transferase
Gene: Protein-coding gene on chromosome 19 (5,830,361 to 5,839,722, reverse strand). Ensembl gene ENSG00000156413.
Subcellular location: Golgi apparatus, Golgi stack membrane; Golgi apparatus; Secreted
Subcellular location (Human Protein Atlas): Golgi apparatus; Predicted to be secreted
Pathways (Reactome):
Metabolism: Lewis blood group biosynthesis
Gene Ontology:
Molecular function: 4-galactosyl-N-acetylglucosaminide 3-alpha-L-fucosyltransferase activity; fucosyltransferase activity; alpha-(1->3)-fucosyltransferase activity
Biological process: ceramide metabolic process; glycosphingolipid biosynthetic process; protein N-linked glycosylation; protein O-linked glycosylation; protein O-linked glycosylation via fucose; glycoprotein biosynthetic process; L-fucose catabolic process; oligosaccharide biosynthetic process; sphingolipid metabolic process
Cellular component: extracellular exosome; extracellular region; Golgi apparatus; Golgi membrane; Golgi cisterna membrane; membrane
Genetic constraint (gnomAD): Loss-of-function variants: 2 observed, 2.33 expected, observed/expected ratio (o/e) 0.86, 90% interval 0.33 to 1.84. That is too few expected variants to judge how well the gene tolerates losing a copy. Missense variants: 454 observed, 508.69 expected, observed/expected ratio (o/e) 0.89, 90% interval 0.83 to 0.96. Synonymous variants: 187 observed, 215.11 expected, observed/expected ratio (o/e) 0.87, 90% interval 0.77 to 0.98.
Homologues: Orthologues: chimpanzee FUT5 (94% identical), dog FUT5 (71% identical), tropical clawed frog fut3 (48% identical), tropical clawed frog fut6 (48% identical), tropical clawed frog fut3 (47% identical), tropical clawed frog fut5 (41% identical), zebrafish fut9b.1 (37% identical), zebrafish fut9b.5 (34% identical), zebrafish fut7 (34% identical), zebrafish fut9b.2 (33% identical), zebrafish fut9d (33% identical), zebrafish fut9b.6 (33% identical), and 15 more. Paralogues in human: FUT5 (89% identical), FUT3 (85% identical), FUT4 (42% identical), FUT7 (39% identical), FUT9 (36% identical), POFUT3 (25% identical), POFUT4 (24% identical).
Diseases named in the same sentence as FUT6 in open-access papers:
FUT6 is named in the same sentence as 40 diseases in open-access papers, as found by Europe PMC text mining. Sharing a sentence is not in itself a finding about the gene and the disease. The quoted sentences say what the papers report.
colorectal cancer (12 papers, 2017 to 2024). A primary or metastatic malignant neoplasm that affects the colon or rectum. "FUT5 and FUT6 have been associated with a PI3K-mediated aggressive phenotype in colorectal cancer." (PMID 35625673, 2022). "As reported, high expression of FUT6 is related to the occurrence and metastasis of a wide range of cancer types, including breast cancer, gastric cancer and colorectal cancer." (PMID 38660262, 2024). "FUT5 and FUT6 are highly expressed in colorectal cancer and promote tumour growth by promoting the proliferation, invasion, migration and angiogenesis of colorectal cancer cells in vivo." (PMID 38807207, 2024). "A recent study has shown that FUT6 promotes the proliferation, migration and invasion colorectal cancer cells." (PMID 36330441, 2022). "Similar to EGF and b-FGF, TGF-β-induced upregulation of FUT3 and FUT6 also leads to overexpression of sialylated Lewis antigens in colorectal cancer cell lines and subsequently to an increased migratory phenotype." (PMID 29527514, 2018). "High expression of FUT6 in colorectal cancer could enhance the migration, proliferation, invasion and angiogenesis of colorectal cancer cells in vivo and thereby promote tumour growth." (PMID 38807207, 2024). "Additionally, lncRNA HOTAIR supports colorectal cancer progression by interacting with miR-326 and FUT6, increasing CD44 fucosylation and stimulating the PI3K/AKT/mTOR pathway." (PMID 36555445, 2022). "Inhibition of FUT3 and FUT6 has been shown to affect TGF-β receptor glycosylation, resulting in decreased fucosylation as well as FUT3/6-associated sialyl Lewis antigens and altered TGF-β-mediated EMT and invasion in colorectal cancer cells." (PMID 30909444, 2019). "Though FUT6 seems to have a preference for the sialylated substrate, here, the results point towards the expression of mainly non-sialylated Lewis antigens via action of fucosylytransferases FUT3 (Lewis A) and FUT4 or FUT6 (Lewis X) in the CDX1high colorectal cancer cell lines analyzed here." (PMID 30909444, 2019). "However, Liang et al13 discovered that FUT6 could promote the growth, invasion, and angiogenesis of colorectal carcinomas via the miR-125a-3p/PI3K/Akt axis." (PMID 39375968, 2024). "In addition, miR-125a-3p modulates FUT5 and FUT6 in colorectal cancer." (PMID 36555445, 2022). "FUT5 and FUT6: MiR-125a-3p can reduce malignancy of colorectal cancer cells by targeting FUT5 and FUT6 and the downstream PI3K-AKT pathway." (PMID 36555445, 2022). "FUT6 produced glycans for tumor cells via the PI3K/Akt signaling pathway, which was regulated by miR-125a-3p in colorectal cancer." (PMID 35127477, 2021).
breast carcinoma (7 papers, 2017 to 2024). "Although FUT6 is involved in the biosynthesis of the cancer associated sLex antigen, it has also been reported that FUT6 down-regulation induced by miR-106b targeting leads to increased invasion of breast cancer cells." (PMID 28481247, 2017). "Downregulation of miR-106b in human breast cancer cells can increase FUT6 expression, leading to a significant decrease in the migration, invasion, and proliferation of cancer cells." (PMID 38807207, 2024). "This decreased expression of FUT6 was found to be involved in the movement, infiltration, and growth of human breast cancer cells." (PMID 39375968, 2024). "This is not in line with literature reporting sLeX to be mainly regulated by FUT6 in CRC as well as breast cancer." (PMID 38670309, 2024). "Downregulation of miR-106b expression in human breast cancer cells increased the expression of FUT6, which led to a significant decrease in the invasion, migration, and proliferation of cancer cells." (PMID 38807207, 2024). "In other reports, the main α1,3/4‐FUTs associated with sLeX biosynthesis in breast cancer included FUT3, FUT6, and FUT7." (PMID 29215790, 2018). "Low expression of FUT6 has been found in breast cancers with high expression of miR-106b." (PMID 38807207, 2024). "Low FUT6 expression was found in breast cancers with high expression of miR-106b." (PMID 38807207, 2024). "Regarding fucosylated glycans synthesized by a range of fucosyltransferases (FUT1-FUT11), previous studies have found that the expression of sLeX is mainly regulated by FUT6 in breast cancer, while FUT7 plays an essential role in the upregulation of sLeX in adult T cell leukemia cells." (PMID 38670309, 2024). "However, in breast cancer cells, low expression of FUT6 regulated by miR-106 b contributes to tumor migration, invasion, and proliferation." (PMID 36330441, 2022).
colon cancer (6 papers, 2010 to 2024). "The two colon cancer cell lines were chosen as recipients of FUT6 and B4GALNT2 enzymes for two reasons." (PMID 32911675, 2020). "In fact, while in colon cancer tissues (where B4GALNT2 levels are low) sLex levels correlate with FUT6 expression, in normal colon (where B4GALNT2 is high), they correlate with the FUT6/B4GALNT2 ratio." (PMID 28241499, 2017). "Since the total tumor RNA was available for patient A, we analyzed the FUT6 mRNA level in patient A's tumor and in other colon tumor and normal tissue samples." (PMID 20711419, 2010). "Thus, we have shown that the SW620 cell line, derived from a lymph node metastasis of colon cancer, transfected with the FUT6 cDNA overexpressed E-selectin ligands." (PMID 33167483, 2020). "They reported that, when EGF was used in colon cancer cell lines, glycosyltransferase, including FUT3, FUT6, and ST3GAL1/3/4, was elevated." (PMID 38528852, 2024). "An RT-PCR analysis showed that FUT6 mRNA was over-expressed only in patent's A tumor but not in any other of the 13 colon tumor and normal tissues." (PMID 20711419, 2010). "Although the molecular bases of sLex overexpression in colon cancer are complex and poorly understood, its last biosynthetic step in colon is mainly, if not exclusively, catalyzed by fucosyltransferase 6 (FUT6)." (PMID 32911675, 2020).
acute myeloid leukaemia (2 papers, 2022 to 2024). "Previous studies have shown that high FUT6 expression is an independent indicator of poor prognosis in patients with acute myeloid leukaemia (AML) and that FUT6 may be a therapeutic target for AML patients." (PMID 38807207, 2024).
head and neck squamous cell carcinoma (2 papers, 2023 to 2024). A squamous cell carcinoma that arises from any of the following anatomic sites: lip and oral cavity, nasal cavity, paranasal sinuses, pharynx, larynx, and salivary glands. "Fucosyltransferase VI (FUT6) modulates the EGFR/ERK/STAT signalling pathway to control head and neck squamous cell carcinoma invasion, migration, proliferation and EGF-induced EMT." (PMID 37569598, 2023).
prostate carcinoma (2 papers, 2021 to 2025). A carcinoma that arises from epithelial cells of the prostate gland. "Using genetic engineering techniques, we introduced α-1,3-fucosyltransferase 6 (Fut6), a key protein involved in prostate cancer bone metastasis, and identified exosomes expressing Fut6 (F6-exo) with bone-targeting capabilities." (PMID 39944529, 2025). "Altered expression of FUT8 and FUT6 is an important feature in several cancers such as high-grade prostate cancer and breast cancer." (PMID 34359624, 2021). "Inspired by studies on prostate cancer bone metastasis, we selected Fut6 as the engineering gene." (PMID 39944529, 2025). "Furthermore, expression of FUT6 might trigger prostate cancer cell trafficking through an E-selectin-dependent mechanism." (PMID 34359624, 2021).
vitamin B12 deficiency (2 papers, 2018 to 2022). A disease characterized by low serum levels of vitamin B12, either inherited or acquired. "FUT6 gene was located on chromosome 19, which encoded a Golgi stack membrane protein, and associated with vitamin B12 deficiency." (PMID 36275653, 2022). "In light of the potential physiological link between the FUT6 gene and vitamin B12 deficiency, three studies investigated the relationship between variants in the FUT6 gene and vitamin B12 status." (PMID 29445423, 2018).
Allergy (1 paper, 2021). An allergy is an immune response or reaction to substances that are usually not harmful. "As the main function of basophils is to mediate allergy and hypersensitivity reactions, FUT6 deficiency should also correlate with allergy-related parameters." (PMID 34215830, 2021). "Thus, the lack of sLex expression on basophils caused by FUT6 deficiency directly translates into functional defects of the IgE-mediated allergy response." (PMID 34215830, 2021).
bone metastasis (1 paper, 2021). Transfer of a neoplasm from its primary site to bones. "The increment of fucosylation in PCa patients seems to be correlated with the up-regulation of fucosyltransferases, the enzymes involved in fucosylation process; for instance, the fucosyltransferase 6 (FUT6) is over-expressed in patients with bone metastasis." (PMID 34069262, 2021).
breast tumors (1 paper, 2016). "Previous reports have indeed suggested that expression of SLex and E-Selectin ligands was dependant on FUT3/FUT6 expression in breast tumors and cell lines." (PMID 26908442, 2016).
cervical carcinoma (1 paper, 2024). A carcinoma arising from either the exocervical squamous epithelium or the endocervical glandular epithelium. "Bai et al14 proposed that circSND1 activates FUT6 expression through a mechanism that promotes the malignant behavior of cervical carcinomas." (PMID 39375968, 2024).
galactosaemia (1 paper, 2018). "Modification of branched N-glycans structures such as bisecting GlcNAc, β-1,6-GlcNAc and core fucose (α-1,6-fucose), the enzymatic products of MGAT3 and FUT6 genes, shown to be abnormal in galactosaemia, are highly associated with biological functions involving cell adhesion." (PMID 30231941, 2018).
gallstones (1 paper, 2018). Solid crystalline precipitates in the biliary tract, usually formed in the gallbladder, resulting in the condition of cholelithiasis. "Among the novel gallstone variants, two are in fucosyltransferase genes (FUT2 and FUT6)." (PMID 30504769, 2018).
head and neck cancer (1 paper, 2024). A primary or metastatic malignant neoplasm affecting the head and neck. "The aim of this study was to determine the role of lncRNA PART1 and downstream FUT6 in tumorigenesis and progression of head and neck cancer (HNC)." (PMID 38807207, 2024).
meningioma (1 paper, 2024). A generally slow growing tumor attached to the dura mater. "We found that the respective expression of FUT2, FUT3, FUT6, and FUT7 was also increased in the malignant meningiomas—HKBMM and IOMM-Lee." (PMID 38274327, 2024). "High expression of FUT1, FUT2, FUT3, FUT6, FUT7, and FUT8 in malignant meningioma cell lines—HKBMM and IOMM-Lee—may represent a fucosylation signature of mucin-type O-linked glycosylation in malignant meningiomas." (PMID 38274327, 2024). "FUT1, FUT2, FUT3, FUT6, FUT7, and FUT8 were highly increased in malignant meningioma cell lines." (PMID 38274327, 2024).
non-alcoholic fatty liver disease (1 paper, 2021). "Significant overexpression of FUT6 has been reported in patients with non-alcoholic steatohepatitis (NASH), which is a progressive form of non-alcoholic fatty liver disease (NAFLD)." (PMID 33765222, 2021).
non-small cell lung carcinoma (1 paper, 2024). A group of at least three distinct histological types of lung cancer, including non-small cell squamous cell carcinoma, adenocarcinoma, and large cell carcinoma. "A previous study showed that FUT6 overexpression in non-small-cell lung cancer cells affected the growth, movement, as well as infiltration of tumor." (PMID 39375968, 2024).
oral cancer (1 paper, 2021). "In this study, we examined the mRNA expressions of fucosidase (FUCA1) and FUTs (FUTs (FUT3, FUT4, FUT5, FUT6, FUT8) in human oral cancer tissues." (PMID 34703796, 2021). "Therefore, the present investigation was aimed to evaluate the clinical significance of mRNA expressions of various fucosyltransferses (FUT3, FUT4, FUT5, FUT6, FUT8) and fucosidases (FUCA1) in oral cancer progression." (PMID 34703796, 2021).
pancreatic cancer (1 paper, 2020). "After the multi-step validation, we identified B3GNT3, B4GALNT3, FUT3, FUT6, GCNT3 and MGAT3 as top-upregulated genes in aggressive pancreatic cancer cell lines Capan-1 and HPAF/CD18." (PMID 32203219, 2020).
tongue cancer (1 paper, 2021). A malignant neoplasm affecting the tongue. "Further, we have documented that the treatment of tobacco metabolites such as 4-NQO, NNK, Benzopyrene lead to the increase in FUT4, FUT5, FUT6, and FUCA1 transcripts in a dose dependent manner in treated tongue carcinoma cells." (PMID 34703796, 2021).